TXNIP (thioredoxin interacting protein)
Diseases named in the same sentence as TXNIP in open-access papers (continued):
Sharing a sentence is not in itself a finding about the gene and the disease.
non-small cell lung carcinoma (11 papers, 2020 to 2024). A group of at least three distinct histological types of lung cancer, including non-small cell squamous cell carcinoma, adenocarcinoma, and large cell carcinoma. "Down-regulation of the lncRNA LHFPL3-AS2 reduces its specific interaction with SFPQ, leading to more SFPQ binding to the TXNIP promoter, causing transcriptional repression of TXNIP, which ultimately promotes metastasis in non-small cell lung cancer." (PMID 38558328, 2024). "LHFPL3-AS2 is a relatively uncharacterized lncRNA, with one recent publication indicating that it suppresses metastasis of non-small cell lung cancer (NSCLC) by interacting with SFPQ to regulate TXNIP expression." (PMID 37993670, 2023). "In the meantime, our research group conducted gene sequencing of early-stage non-small cell lung cancer and found that TXNIP was highly correlated with cisplatin resistance." (PMID 35414060, 2022). "The study has found that inhibition of PI3K/AKT signaling by tyrosine kinase inhibitors (TKI) leads to increased TXNIP expression in non-small-cell lung cancer (NSCLC) tissue." (PMID 35450411, 2022). "Our previous study showed butyrate-induced cell death and cell cycle arrest on non-small-cell lung cancer line A549 partially via thioredoxin interacting protein (TXNIP), which expression was highly induced by the treatment of NaBu." (PMID 33274003, 2020). "In addition, inhibition of constitutive PI3K/Akt signaling increases the expression of TXNIP in non-small-cell lung cancer, suggesting the potential significance of this mechanism in tumorigenesis." (PMID 36366411, 2022). "Previously, we found TXNIP was highly induced in a non-small-cell lung cancer cell line A549." (PMID 33274003, 2020). "For instance, miR-411-5p accelerates non-small cell lung cancer development by suppressing SPRY4 and TXNIP." (PMID 34903711, 2021). "In non-small cell lung cancer (NSCLC), for example, a proportion of adenocarcinomas showed higher TXNIP levels but not any squamous cell carcinomas." (PMID 33081035, 2020).
colitis (10 papers, 2013 to 2026). Inflammation of the colon. "During colitis, the dissociated TXNIP was bound to NLRP3, and this interaction was blocked by MitoQ treatment." (PMID 23915129, 2013). "Additionally, Ox-LDL/CD36/ ROS generation/TXNIP upregulation/NLRP3 inflammasome activation axis warrants investigation during the course of colitis." (PMID 33917884, 2021). "Therefore, we concluded that activation of NLRP3 inflammasome during colitis is dependent on the interaction of TXNIP and NLRP3, and that this activation is mediated by mtROS." (PMID 23915129, 2013). "Inhibiting TXNIP in macrophages via reducing ROS could restrain DSS-induced colitis." (PMID 35624485, 2022). "Therefore, we hypothesized that binding of TXNIP to NLRP3 activates the inflammasome, which causes autocleavage of caspase-1 and the release of mature cytokines IL-1 beta and IL-18 during colitis." (PMID 23915129, 2013). "ER stress plays a key role in human diseases, including colitis and acute pancreatitis, by increasing the release of proinflammatory factors such as IL-1β, cleaved caspase-1, and TNF-α which is elicited by TXNIP during neuroinflammation." (PMID 34790063, 2021). "In the present study, we showed that MitoQ suppresses ROS-promoted dissociation of TXNIP from TRX, inhibits the interaction between TXNIP and NLRP3, and significantly decreases levels of IL-1 beta and IL-18 in the colons of mice with DSS-induced colitis." (PMID 23915129, 2013).
coronary heart disease (10 papers, 2016 to 2023). "A study in the Chinese Han population reported that TXNIP single nucleotide polymorphisms individually and cumulatively increased the risk of coronary heart disease by regulating TXNIP expression and gene-environment interactions." (PMID 36588561, 2022). "Clinically, genetic association studies have shown that polymorphisms affecting TXNIP expression are linked to hypertension and arterial stiffness and increase the risk of coronary heart disease." (PMID 33567593, 2021). "Peripheral blood lymphocytes from coronary artery disease (CAD) patients show overexpression of TXNIP induced by the loss of DNA methylation levels in its 3′UTR regulatory region, promoting inflammasome activation." (PMID 34829842, 2021). "A study among the Chinese Han population reported that TXNIP single-nucleotide polymorphisms independently and gradually increase the risk of coronary heart disease by regulating TXNIP expression and gene-environment interactions." (PMID 31687078, 2019). "Finally, in this population, coronary artery disease risk is also found associated with the TXNIP DNA methylation level independently of TXNIP rs7211 and 7212 variants." (PMID 33567593, 2021). "Because the TXNIP is a ubiquitously expressed protein, we speculate that abnormal expression of TXNIP in leukocytes may be associated with coronary heart disease." (PMID 30034557, 2018). "Interestingly, the same variants of TXNIP rs7212 and rs7211 are significantly associated with increased coronary artery disease risk, and the cumulative effects of these two SNPs have been described on coronary artery disease risk and the severity of coronary atherosclerosis in a Chinese population." (PMID 33567593, 2021). "We enrolled 100 patients with coronary heart disease (CHD) and found that plaque burden, TXNIP expression, and inflammatory chemokine levels were higher in smokers than non-smokers." (PMID 33626512, 2021).
Hepatic steatosis (10 papers, 2016 to 2025). Steatosis is a term used to denote lipid accumulation within hepatocytes. "A recent study validated that PF’s reversal of abnormal liver function and hepatic steatosis in db/db mice is linked to the inhibition of the TXNIP/NLRP3 signaling pathway, indicating TXNIP as a possible target of PF." (PMID 40260393, 2025). "Fasting also induces upregulation of thioredoxin-interacting protein (TXNIP) expression and mice deficient of this protein (TXNIP-KO mice) was shown to develop severe hypoglycemia, hyperlipidemia and liver steatosis (LS)." (PMID 35314758, 2022). "Together, these results suggest that SalA-mediated protection against HFD-induced hepatic steatosis partly related to modulation of the hepatic TXNIP-ChREBP pathway." (PMID 27345365, 2016). "Taken together, these in vivo and in vitro results demonstrate that SalA ameliorates HFD-induced hepatic steatosis partially via regulation of the TXNIP/ChREBP pathway." (PMID 27345365, 2016). "The identification of a CHIP region that regulates TXNIP expression may reveal promising therapeutic strategies for the treatment of hepatic steatosis." (PMID 36830016, 2023). "Thus, TXNIP may serve as a new therapeutic target for the treatment of Reye-like syndrome, and deficiency in TXNIP may be associated with the mechanism of fatty liver caused by other clinical conditions, such as ALD or NAFLD, or drug-induced fatty liver." (PMID 35314758, 2022). "Salvianolic acid A inhibits the nuclear translocation of Carbohydrate Response Element-Binding Protein (ChREBP) by suppressing Thioredoxin-Interacting Protein (TXNIP), thereby improving high-fat diet (HFD)-induced hepatic steatosis." (PMID 41154556, 2025). "Thioredoxin-interacting protein (TXNIP) is a key regulator of glucose metabolism disorders, cholesterol accumulation, and fatty acid synthesis in the liver, modulating ERS, and leading to hepatic steatosis and inflammation." (PMID 40292292, 2025).
myocardial infarction (10 papers, 2018 to 2023). Gross necrosis of the myocardium, as a result of interruption of the blood supply to the area, as in coronary thrombosis. "The critical cysteines for thioredoxin binding have been identified on TXNIP, and recent data shows that the C247S mutation protects against myocardial infarction in mice whilst also regulating adipogenesis." (PMID 37794178, 2023). "As a matter of fact, increased endothelial expression of TXNIP was found in diabetic hearts, which correlated well with the fact that insufficient angiogenesis aggravated cardiac remodeling and caused poor survival following myocardial infarction." (PMID 33567593, 2021). "Salvianolate reduces atrial fibrillation by inhibiting the TGF-β1/Smad2/3 and TXNIP/NLRP3 inflammasome signaling pathways in rats after myocardial infarction, thereby inhibiting atrial fibrosis." (PMID 36909150, 2023). "This reduced the myocardial infarct size and apoptosis by decreasing the expression of the thioredoxin-interacting protein (TXNIP)." (PMID 34066757, 2021). "Moreover, in rats, treatment with resveratrol, a well-known inhibitor of TXNIP, is reported to be cardioprotective and to promote revascularization in a model of myocardial infarction." (PMID 33567593, 2021). "Moreover, circulating TXNIP levels are also found to be increased after a heart attack induced by irradiation with 8Gy in rodents and is associated with reduced TRX and TRX reductase levels, with increased cardiac TXNIP content and decreased cardiac antioxidant enzymes expression." (PMID 33567593, 2021). "Salvianolate treats myocardial infarction by inhibiting the TGF-β1/Smad2/3 and TXNIP/NLRP3 inflammasome signaling pathways." (PMID 36909150, 2023).
cervical cancer (9 papers, 2010 to 2024). A primary or metastatic malignant neoplasm involving the cervix. "According to recent research, human papillomavirus (HPV) E6/E7 oncoproteins promoted cell growth and substantially prevented cell death in cervical cancer by methylating the TXNIP promoter and down-regulating the expression of TXNIP." (PMID 36366411, 2022). "The increase in UHRF1 in cervical cancer (CC) tissue promotes the hypermethylation of the TXNIP promoter to downregulate the expression of TXNIP, thus promoting carcinogenesis." (PMID 35628460, 2022). "A recent publication notes that TXNIP promoter methylation may mediate the carcinogenesis of human papillomavirus (HPV)-induced cervical cancer." (PMID 35843949, 2022). "Thus, TXNIP is recommended as a potential therapeutic approach for cervical cancer." (PMID 36366411, 2022). "In addition, TXNIP expression revealed could be induced by MondoA and to inhibit cervical cancer cell proliferation, migration, and invasion." (PMID 34484334, 2021).
glioma (9 papers, 2016 to 2025). A benign or malignant brain and spinal cord tumor that arises from glial cells (astrocytes, oligodendrocytes, ependymal cells). "In a recent study, low TxNIP expression in glioma was associated with higher histological grade and shorter patient survival." (PMID 32418115, 2020). "Interestingly, it has been demonstrated that low TXNIP expression in glioma is associated with higher histopathological glioma grade and shorter overall patient survival." (PMID 30248944, 2018). "But, the RT-qPCR results showed that five genes (IKBKB, PDIA4, RCC2, RPL4, and TXNIP) were low expressed in glioma cell lines compared to HA." (PMID 36111134, 2022). "Low expression of TXNIP was observed in high grade glioma tissues by comparing to low grade tumours." (PMID 34433833, 2021). "Thioredoxin-interacting protein (TXNIP) was reported as a tumor-suppressor gene in glioma." (PMID 36111134, 2022). "Upregulation of TXNIP in pterostilbene treated GCs therefore indicates a more complex response in tumor cells perhaps due to altered levels of oxidative stress or an altered metabolic state in glioma." (PMID 27689322, 2016). "In addition, the catalytic subunit brahma related gene 1 (BRG1) of the SWI/SNF complex can maintain the stemness of glioma‐initiating cells by inhibiting the STAT3/TXNIP pathway, resulting in the resistance of glioma‐initiating cells to the chemotherapeutic drugs temozolomide (TMZ) and carmustine." (PMID 37576862, 2023). "In addition, in glioma downregulation of the negative Trx regulator TXNIP has been shown to be associated with higher histopathological glioma grade and shorter overall patient survival." (PMID 30248944, 2018). "A significantly higher expression of both cytoplasmic and nuclear TrxR was observed in grade I gliomas, and grade IV gliomas had the highest TxNIP expression; whereas no significant variation in Trx expression was noted between different grades." (PMID 32418115, 2020).
neuroblastoma (9 papers, 2015 to 2023). Neuroblastoma (NB) is the most common solid, extracranial childhood tumor. "We evaluated the participation of TXNIP in cell death in human MSN neuroblastoma cells treated with Sts." (PMID 37547922, 2023). "Curcumin (10 μmol L-1) inhibits the activation of the TXNIP/NLRP3 pathway by up-regulating AMPK activity in human neuroblastoma SH-SY5Y cells of human neuroblastoma and reducing ROS produced by endoplasmic reticulum stress." (PMID 37153784, 2023). "Co-treatment with polymethoxyflavonoid and tunicamycin led to up-regulation of TXNIP in human neuroblastoma cells." (PMID 33233497, 2020). "In SK-N-SH human neuroblastoma cells, NOB significantly reduces the expression of thioredoxin-interacting protein (TXNIP), which is one crucial factor for endoplasmic reticulum stress resulting in cell apoptosis." (PMID 27761146, 2016). "Detailed analysis remains to be carried out on cooperative binding by different network heterodimers, but initial work supports the idea that MYCN-MAX and MLXIP-MLX can co-occupy the TXNIP promoter region and act to cooperatively augment TXNIP expression in MYC-driven neuroblastoma." (PMID 30054853, 2018). "Interestingly, we noticed glutamine deprivation similarly resulted in TXNIP induction and subsequent decrease in glucose uptake and lactate secretion in MYCN-amplified neuroblastoma cells." (PMID 26528759, 2015). "Whether TXNIP virtually functions downstream of GLS2 to restrict aerobic glycolysis needs further investigation, though we observed prominent induction of this protein in MYCN-amplified neuroblastoma cells upon glutamine starvation and GLS2 knockdown." (PMID 26528759, 2015).
Parkinson disease (9 papers, 2018 to 2025). A progressive degenerative disorder of the central nervous system characterized by loss of dopamine producing neurons in the substantia nigra and the presence of Lewy bodies in the substantia nigra and locus coeruleus. "Cerebral organoids generated from mutated hiPSCs were then found to yield several different phenotypes that were observed with Parkinson’s disease and also used to identify a disease relevant gene encoding for the thioredoxin interacting protein (TXNIP)." (PMID 32671050, 2020). "In Parkinson’s disease, researchers have found that overexpressing TXNIP is available to elevate α-synuclein and block autophagy, thereby exacerbating Parkinson’s disease development." (PMID 34348577, 2021). "Of note, TXNIP knockdown rescued α-synuclein oligomers in LRRK2 p.Gly2019Ser knock-in 3D organoids, suggesting the importance of this gene in the development of LRRK2-associated Parkinson’s disease." (PMID 39273694, 2024). "In conclusion, lncZFAS overexpression inhibited the TXNIP/MIB1 E3 ubiquitin ligase/NLRP3 pathway through direct interference with miR590-3p, which shows a novel research avenue in exploring the mechanism of inflammasome activation and pyroptosis in Parkinson’s disease." (PMID 34775541, 2022).
steatosis (9 papers, 2021 to 2025). Increased lipid within the cytoplasm of cells. "IHC revealed markedly increased TXNIP expression in patients with alcohol-associated steatosis and fibrosis compared with that in healthy controls." (PMID 38169654, 2024). "The degree of TXNIP expression was positively correlated with the percentage of macro-fat in alcoholic patients with steatosis." (PMID 38169654, 2024). "As a result, we reasoned that steatosis increased the generation of ROS in hepatocytes, changed the expression of the AMPK/FOXO3/TXNIP signaling cascade, created an imbalance between pro-oxidants and antioxidants, and resulted in oxidative stress." (PMID 36144229, 2022). "In contrast, mice lacking TXNIP exhibit exacerbated steatosis and liver inflammation when fed an MCD diet, suggesting a negative regulatory role of TXNIP on NLRP3 and its protective role in MASH." (PMID 39917567, 2025). "Moreover, thioredoxin interacting protein (TXNIP/VDUP1) mediates the activation of AMPK, inhibition of mTOR, and nuclear translocation of TFEB which ultimately resulted MCD diet-induced steatosis, inflammation, and fibrosis." (PMID 34711912, 2021).
viral infection (9 papers, 2018 to 2025). "Taken together, these results indicate that TXNIP negatively regulates MAVS aggregation during viral infection, thereby attenuating activation of downstream signaling pathways such as TBK1 and IRF3." (PMID 40628121, 2025). "Currently, the regulatory role of TXNIP in viral infections, particularly in HSV-1 or DENV infection, remains poorly understood, making it essential to deeply explore its specific regulatory mechanisms." (PMID 40628121, 2025). "Although this study elucidated the mechanism of TXNIP in viral infections and validated the antiviral efficacy of Luteolin, several questions remain to be addressed." (PMID 40628121, 2025). "In the area of viral infection, one study suggested that TXNIP activated Epstein-Barr virus (EBV) replication by activating NLRP3 pathway." (PMID 40628121, 2025). "To investigate the effect of TXNIP on type I interferon responses during viral infection, we examined the expression levels of IFN-β and IFN-α following HSV-1 infection." (PMID 40628121, 2025). "Conversely, TXNIP knockout enhanced MAVS aggregation in response to viral infection, further supporting its inhibitory role." (PMID 40628121, 2025). "In this study, we investigated the role of TXNIP in viral infection and its potential as a therapeutic target." (PMID 40628121, 2025). "Collectively, these findings indicate that the role of TXNIP in viral infection remains incompletely understood and requires further clarification." (PMID 40628121, 2025). "It plays a vital role in immune responses, viral infections, and cell death, primarily through its interaction with thioredoxin-interacting protein." (PMID 39766807, 2024). "TXNIP also appears to be indispensable in the restriction of T cell (mainly in CD4+T cells) and germinal center B cell expansion following viral infections, a process that relies on Trx1/TXNIP balance." (PMID 37794178, 2023). "After 72 hours, the efficiency of virus infection was determined by observing the green fluorescence with an inverted fluorescence microscope at 300× magnification and then verified by TXNIP mRNA and protein expressions." (PMID 32039564, 2020). "By comparing the regulatory roles of TXNIP across different viral infections, a theoretical foundation for developing broad-spectrum antiviral drugs could be established." (PMID 40628121, 2025). "In fact, some evidence suggests that downregulating TXNIP may have a sensitizing effect on virus infection." (PMID 36969187, 2023). "In addition, in the case of HCV, TXNIP has been shown to negatively affect virus replication, further indicating the potential significance of this protein to the regulation of viral infections." (PMID 32017809, 2020). "The reduced responsive cells also had upregulated TXNIP, which has been demonstrated to reduce effector functions in CD8 T cells in viral infection." (PMID 38008725, 2023). "While this study primarily focused on the role of TXNIP in HSV-1 and DENV2 infections, future research could explore its involvement in other viral infections." (PMID 40628121, 2025). "Etiological stratification revealed that overall TXNIP expression was higher in viral infection- (both HCV and HBV) related HCCs than non-viral cases (p:0.0001)." (PMID 30627326, 2018). "Etiological stratification of our HCC patients displays a similar pattern where overall TXNIP expression is significantly higher in viral infection- (both HCV or HBV) related HCCs than in non-viral cases." (PMID 30627326, 2018).